NAXD-AS1 (NAXD antisense RNA 1)
Synonyms: AL139385.1
Gene: Long non-coding RNA gene on chromosome 13 (110,613,082 to 110,616,353, reverse strand). Ensembl gene ENSG00000275880.
Diseases named in the same sentence as NAXD-AS1 in open-access papers:
NAXD-AS1 is named in the same sentence as 1 disease in open-access papers, as found by Europe PMC text mining. Sharing a sentence is not in itself a finding about the gene and the disease.
NAXD-AS1 shares sentences with these, for which no sentence is quoted: lung carcinoma (1 paper).